ANKRD16 (ankyrin repeat domain 16)
Description:
Required to prevent the misactivation of serine (Ser) with tRNA(Ala) by promoting the hydrolysis of Ser-mischarged tRNA(Ala), thereby playing a role in translational fidelity. Binds directly to the catalytic domain of AARS/AlaRS and captures Ser that is misactivated by AARS/AlaRS, preventing the charging of Ser adenylates to tRNA(Ala) and precluding Ser misincorporation in nascent peptides.
Synonyms: DKFZP434N1511
Tractability: PROTAC: ubiquitination databases record sites on it.
Gene: Protein-coding gene on chromosome 10 (5,861,616 to 5,889,906, reverse strand). Ensembl gene ENSG00000134461.
Subcellular location: Cytoplasm; Nucleus
Subcellular location (Human Protein Atlas): Endoplasmic reticulum
Gene Ontology:
Biological process: tRNA modification
Cellular component: cytoplasm; nucleus
Genetic constraint (gnomAD): Loss-of-function variants: 29 observed, 29.17 expected, observed/expected ratio (o/e) 0.99, 90% interval 0.74 to 1.36. The upper end of that interval is the gene's LOEUF score, 1.36, which puts it in group 5 of 6, group 1 being the genes least tolerant of losing a copy. Missense variants: 417 observed, 378.45 expected, observed/expected ratio (o/e) 1.1, 90% interval 1.02 to 1.2. Synonymous variants: 179 observed, 153.5 expected, observed/expected ratio (o/e) 1.17, 90% interval 1.03 to 1.32.
Homologues: Orthologues: chimpanzee ANKRD16 (99% identical), macaque ANKRD16 (97% identical), guinea pig ANKRD16 (85% identical), mouse Ankrd16 (82% identical), pig ANKRD16 (80% identical), rat Ankrd16 (80% identical), dog ANKRD16 (76% identical), zebrafish ankrd16 (59% identical), tropical clawed frog ankrd16 (54% identical), Caenorhabditis elegans ZK792.4 (20% identical). Paralogues in human: ASB1 (24% identical).
Diseases named in the same sentence as ANKRD16 in open-access papers:
ANKRD16 is named in the same sentence as 5 diseases in open-access papers, as found by Europe PMC text mining. Sharing a sentence is not in itself a finding about the gene and the disease. The quoted sentences say what the papers report.
cancer (1 paper, 2025). A tumor composed of atypical neoplastic, often pleomorphic cells that invade other tissues. "The probability of these six genes to be mutated in normal tissue adjacent to cancer is CPA6 (3.85%), ZNF888 (46.15%), SH3BP1 (76.92%), ANKRD16 (30.77%), ATN1 (11.54%), and C4orf54 (80.77%)." (PMID 40688112, 2025).
renal disorders (1 paper, 2023). "ANKRD16 was suggested as a candidate gene for IgAN in the Korean population, although its mutant protein was reported to be associated with Purkinje cell degeneration and had not been linked to renal disorders before." (PMID 37958966, 2023).
ANKRD16 also shares sentences with these, for which no sentence is quoted: breast carcinoma (1 paper); colon cancer (1); neurological diseases (1).